MIR663B (microRNA 663b)
Synonyms: hsa-mir-663b; MIRN663B; mir-663b
Gene: MicroRNA gene on chromosome 2 (132,256,966 to 132,257,080, reverse strand). Ensembl gene ENSG00000221288.
Gene Ontology:
Biological process: miRNA-mediated post-transcriptional gene silencing
Diseases named in the same sentence as MIR663B in open-access papers:
MIR663B is named in the same sentence as 3 diseases in open-access papers, as found by Europe PMC text mining. Sharing a sentence is not in itself a finding about the gene and the disease. The quoted sentences say what the papers report.
cancer (1 paper, 2024). A tumor composed of atypical neoplastic, often pleomorphic cells that invade other tissues. "Recent studies have highlighted the potential significance of MIR663B in cancer progression and treatment." (PMID 39118043, 2024).
MIR663B also shares sentences with these, for which no sentence is quoted: hepatocellular carcinoma (1 paper); nasopharyngeal carcinoma (1).